SULT1C4 (sulfotransferase family 1C member 4)
Description:
Sulfotransferase that utilizes 3'-phospho-5'-adenylyl sulfate (PAPS) as sulfonate donor to catalyze the sulfate conjugation of phenolic compounds. Can also sulfonate estrogenic compounds, however, the dietary flavonoids (phytoestrogen) and environmental estrogens, like bisphenol A are better substrates than 17beta-estradiol (E2). Mediates the sulfation of doxorubicin and its analog epirubicin, two antitumor anthracyclines.
Synonyms: SULT1C2; SULT1C
Tractability: Small molecule: a structure with a bound ligand is known.
Target class: Enzyme; Transferase
Gene: Protein-coding gene on chromosome 2 (108,377,911 to 108,388,989, forward strand). Ensembl gene ENSG00000198075.
Subcellular location: Cytoplasm, cytosol
Subcellular location (Human Protein Atlas): Cytosol
Pathways (Reactome):
Drug ADME: Paracetamol ADME
Metabolism: Cytosolic sulfonation of small molecules
Gene Ontology:
Molecular function: aryl sulfotransferase activity; sulfotransferase activity; steroid sulfotransferase activity
Biological process: 3'-phosphoadenosine 5'-phosphosulfate metabolic process; doxorubicin metabolic process; ethanol catabolic process; flavonoid metabolic process; sulfation; xenobiotic metabolic process; sulfur compound metabolic process
Cellular component: cytosol
Genetic constraint (gnomAD): Loss-of-function variants: 30 observed, 30.66 expected, observed/expected ratio (o/e) 0.98, 90% interval 0.73 to 1.33. The upper end of that interval is the gene's LOEUF score, 1.33, which puts it in group 5 of 6, group 1 being the genes least tolerant of losing a copy. Missense variants: 360 observed, 334.93 expected, observed/expected ratio (o/e) 1.07, 90% interval 0.99 to 1.17. Synonymous variants: 108 observed, 109.08 expected, observed/expected ratio (o/e) 0.99, 90% interval 0.85 to 1.16.
Homologues: Orthologues: chimpanzee SULT1C4 (99% identical), macaque SULT1C4 (95% identical), dog SULT1C4 (83% identical), pig SULT1C4 (79% identical), tropical clawed frog sult1c4 (51% identical), tropical clawed frog sult1c3 (49% identical), zebrafish sult1st6 (49% identical), zebrafish sult1st5 (48% identical), Drosophila melanogaster St3 (30% identical), Drosophila melanogaster St4 (29% identical), Drosophila melanogaster St1 (28% identical). Paralogues in human: SULT1C2 (61% identical), SULT1C3 (56% identical), SULT1A2 (53% identical), SULT1A3 (53% identical), SULT1A4 (53% identical), SULT1A1 (52% identical), SULT1B1 (52% identical), SULT1E1 (47% identical), SULT2A1 (35% identical), SULT2B1 (34% identical), SULT4A1 (32% identical), SULT6B1 (29% identical).
Diseases named in the same sentence as SULT1C4 in open-access papers:
SULT1C4 is named in the same sentence as 5 diseases in open-access papers, as found by Europe PMC text mining. Sharing a sentence is not in itself a finding about the gene and the disease. The quoted sentences say what the papers report.
epilepsy (1 paper, 2025). A brain disorder characterized by episodes of abnormally increased neuronal discharge resulting in transient episodes of sensory or motor neurological dysfunction, or psychic dysfunction. "There is evidence that SULT1C4, NAALAD2, and ADGRV1 participate in neurotransmitter regulation, glutamate dysregulation in schizophrenia, and epilepsy and audiovisual disorders." (PMID 40428414, 2025).
steatosis (1 paper, 2013). Increased lipid within the cytoplasm of cells. "However, only two SULT isoforms, SULT1C4 and SULT4A1, whose regulation and function are largely unknown, have increased mRNA and protein levels in human NASH samples compared to control and steatosis samples." (PMID 23346097, 2013).
SULT1C4 also shares sentences with these, for which no sentence is quoted: intrahepatic cholangiocarcinoma (1 paper); Obesity (1); schizophrenia (1).